NES (nestin)
Diseases named in the same sentence as NES in open-access papers (continued):
Sharing a sentence is not in itself a finding about the gene and the disease.
Alzheimer disease (7 papers, 2019 to 2024). A progressive, neurodegenerative disease characterized by loss of function and death of nerve cells in several areas of the brain leading to loss of cognitive function such as memory and language. "It has also been reported that PIAS3 reduces the activated form of STAT3, increases the activity of the downstream Nestin/Nrf2/HO‐1 pathway, and inhibits damage in Alzheimer's disease model SH‐SY5Y cells." (PMID 39496070, 2024). "In addition, in a mouse model of Alzheimer’s disease (AD), it has been reported that the expression of the mitochondrial transport and dynamics regulator Miro2, which is degraded through PINK1/Parkin-dependent mitophagy, was decreased in Nestin-positive cells of the hippocampus." (PMID 36816109, 2023).
brain injury (7 papers, 2012 to 2025). Acute and chronic (see also brain INJURIES, CHRONIC) injuries to the brain, including the cerebral hemispheres, CEREBELLUM, and brain STEM. "However, it is difficult to determine whether those nestin-deficient NSCs are capable of completing the repair task in irradiation-induced brain injury." (PMID 36551187, 2022). "Nestin immunoreactive cells have been detected at the cervical, dorsal, and lumbar levels in subjects who died after a brain trauma, which indicates the existence of neural progenitors differentiating into neurons in the SC of these subjects." (PMID 40004100, 2025). "1.PV+ ependymal cells promote wound-healing.a positive correlation between the percentage of nestin+ ependymal cells and post-injury survival time in mice after brain trauma." (PMID 37008045, 2023). "In the case of severe brain injuries, it is likely that GH administration and rehabilitation induce significant nestin and actin reexpression in the undamaged contralateral motor cortex." (PMID 29755514, 2018). "Therefore, Homer1 conditional knockout mice (Homer1flox/flox/Nestin-Cre+/−) were constructed to investigate the protective role of Homer1 protein in ischemic brain injury." (PMID 38091015, 2024).
acute myeloid leukemia (6 papers, 2016 to 2023). Acute myeloid leukemia (AML) is a group of neoplasms arising from precursor cells committed to the myeloid cell-line differentiation. "Future work should address the causal contribution of Nestin+ cells in acute myeloid leukemia development, and its potential use as target for novel drug development." (PMID 29541793, 2018). "We have studied the contribution of nestin+ BM mesenchymal stem cells (BMSCs) to MLL-AF9-driven acute myeloid leukemia (AML) development and chemoresistance in vivo." (PMID 32966766, 2020). "reveal that nestin+ bone marrow stromal cells directly contribute to leukemogenesis and chemotherapy resistance in an in vivo model of acute myeloid leukemia." (PMID 32966766, 2020). "In their model, development of acute myeloid leukemia disrupts neural fibers and the quiescence of Nestin+ cells, leading to their expansion by 3.8-fold with osteoblastic priming ex vivo." (PMID 29541793, 2018). "Another intriguing survival pathway in MPNs has been described by Forte and coworkers, suggesting the contribution of Nestin+ BM-MSCs in acute myeloid leukemia (AML) development and chemoresistance in vivo." (PMID 36910610, 2023). "A detailed study of disseminated acute myeloid leukemia (AML) stem cells revealed that the arrival of AML stem cells in the bone marrow disrupts sympathetic nerves, destroying periarteriolar nestin+ HSC niche cells and ultimately depleting HSC niches." (PMID 28085223, 2017).
cervical carcinoma (6 papers, 2008 to 2024). A carcinoma arising from either the exocervical squamous epithelium or the endocervical glandular epithelium. "To examine the role of nestin in cervical cancer cells, we stably transfected expression vectors containing nestin cDNA into ME-180 cells." (PMID 22580387, 2012). "Increased nestin expression in cervical cancer cell lines stimulated colony and sphere formation in vitro." (PMID 22580387, 2012). "In contrast to these malignant tumors, nestin was expressed in all cervical cancer cases, unrelated to their histological type." (PMID 22580387, 2012). "To examine the roles of nestin in cervical cancer cells, we prepared nestinoverexpressing ME-180 cells." (PMID 22580387, 2012). "Although the etiology of nestin expression pattern in cervical cancer is unclear, we suggest that nestin may play a fundamental and important role in cervical carcinogenesis." (PMID 22580387, 2012). "We found that nestin was expressed in all cervical cancer specimens." (PMID 22580387, 2012). "Nestin was detected in all cases of invasive cervical cancer." (PMID 22580387, 2012). "Nestin mRNA was expressed in CaSki and ME-180 cervical cancer cell lines." (PMID 22580387, 2012). "In the co‐culture system of cervical cancer cells and SCs, signals from the cancer cells markedly enhanced the expression of GFAP, Vimentin and nestin in SCs." (PMID 37830980, 2023). "In summary, nestin expression correlates with CIN progression and was expressed in all cervical cancer specimens examined." (PMID 22580387, 2012). "We performed immunohistochemical and in situ hybridization analyses of nestin in 26 cases for each stage of CIN and 55 cervical cancer tissue samples." (PMID 22580387, 2012). "In this study, we determined the expression and role of nestin in cervical intraepithelial neoplasia (CIN) and cervical cancer." (PMID 22580387, 2012). "Furthermore, protein and mRNA level of Nestin, a neural stem cell marker, was increased in RSC96 cells co-cultured with cervical cancer cells by transwell analysis, suggesting the reprograming of Schwann cells." (PMID 39214988, 2024). "However, the expression and role of nestin in cervical intraepithelial neoplasia (CIN) and cervical cancer are poorly understood." (PMID 22580387, 2012). "Although phosphothreonine was reported in samples of Nestin from an immortalized rat cell line and human HeLa cells (cervical carcinoma), we did not detect the phosphorylation of threonine residues in the Nestin proteins from our samples." (PMID 23028390, 2012). "After mmunohistochemical analysis, nestin protein was detected in cancer cells of both the nonkeratinizing and keratinizing types in all examined cervical cancer samples." (PMID 22580387, 2012).
Cognitive impairment (6 papers, 2019 to 2025). Abnormal cognition is characterized by deficits in thinking, reasoning, or remembering. "Reduced hippocampal neurogenesis induced by nestin deficiency, a cell proliferation marker, aggravates memory and cognitive deficits in APP/PS1 mice." (PMID 35956303, 2022).
depression (6 papers, 2015 to 2021). "Our study demonstrated that STC1 elevated the numbers of BrdU- and Nestin-positive cells in rats with depression-like behaviors, suggestive of its beneficial role in neurogenesis." (PMID 34194345, 2021). "To correlate the association between depression and related mood disorders with adult hippocampal neurogenesis, we independently subjected wild-type C57BL/6NCrl and Nestin-GFP transgenic mice to a 10-day CSDS paradigm." (PMID 33182385, 2020). "The expression levels of astrocyte markers (glial fibrillary acidic protein (GFAP), synemin-α, synemin-β, vimentin, nestin) in isolated gray matter from postmortem ACC and DLPFC were determined to investigate the possible involvement of astrocytes in depression." (PMID 31798416, 2019).
lymph node metastasis (6 papers, 2014 to 2021). "They found that nestin expression was significantly associated with lymph node metastasis, stage, and OS in NSCLC patients." (PMID 34943921, 2021). "Nestin positivity was observed in 15.8% of patients; positivity was significantly associated with SCCs, poor differentiation, intratumoral vascular invasion, lymph node metastasis, intratumoral lymphatic invasion, pleural invasion, and a poor prognosis." (PMID 34943921, 2021). "Nestin immunoreactivity significantly correlated with tumor size, lymph node metastasis, and poor survival in patients with ADCs." (PMID 34943921, 2021). "Nestin was observed in most tumor cells and was significantly associated with poor differentiation, ADC, lymph node metastasis, microvessel density, and lymphatic vessel density." (PMID 34943921, 2021). "Nestin/Oct-4 co-expression was significantly correlated with poor prognosis, younger age, lymph node metastasis, and TNBCs." (PMID 32467665, 2020). "For Nestin, its protein expression was correlated with lymph node metastasis and stage." (PMID 27150062, 2016). "We found that the presence of nestin mRNA was increased in the early stages of cancer (T2N0 or T3N0) and advanced cancer with lymph node metastasis (T4N1)." (PMID 25371063, 2015). "Lymph node metastases, nestin expression, and patient age were independent negative prognostic factors." (PMID 34943921, 2021). "Nestin positivity was closely associated with earlier age for the onset of disease, higher histological grade, larger tumor size, and IDC, but not with lymph node metastasis." (PMID 32467665, 2020). "Compared to non-metastasized esophageal carcinoma (without lymph node metastasis), the expression of nestin was markedly higher in metastasized esophageal carcinoma (with lymph node metastasis)." (PMID 29029411, 2017). "In this study, nestin mRNA was overexpressed in the early stages of cancer without lymph node metastasis and in the late stages of cancer with lymph node metastasis, but not in the intermediate stages of cancer." (PMID 25371063, 2015).
nasopharyngeal carcinoma (6 papers, 2015 to 2022). A carcinoma arising from the nasopharyngeal epithelium. "Silencing Nestin expression with shRNA in nasopharyngeal carcinoma cells interrupted doxorubicin-induced DNA damage repair." (PMID 35444938, 2022). "Depleting nestin using shRNA in 5-8F nasopharyngeal carcinoma cells resulted in increased spontaneous DNA damage accumulation and delayed doxorubicin-induced DNA damage repair." (PMID 31126068, 2019).
ovarian carcinoma (6 papers, 2008 to 2022). A malignant neoplasm originating from the surface ovarian epithelium. "Nestin encoded by the NES gene is considered as a marker of angiogenesis and CSC in epithelial ovarian cancer and is associated with poor prognosis of various cancers." (PMID 36110943, 2022). "Expression of stem cell markers (OCT4, SOX2, NANOG, NESTIN, ABCG2, CD133 and CD117) in ovarian cancer (sphere cells) represent their tumorigenic potential, and resistance to cisplatin, paclitaxel, adriamycin and methotrexate, which highlights the significance of “stemness” of cancer cells." (PMID 30121075, 2018).
type I diabetes (6 papers, 2013 to 2023). "This study showed that a disparity in nestin regulation characterized the early pattern of lung remodeling secondary to MI and type I diabetes." (PMID 34943921, 2021). "Nestin downregulation in vascular smooth muscle cells represented an early event in vascular disease in experimental type I diabetes." (PMID 27894297, 2016). "In experimental type I diabetes, nestin downregulation in the heart was identified as an incipient pathophysiological event." (PMID 25139503, 2014). "A similar paradigm was reported following renal damage secondary to experimental type I diabetes as nestin expression was reduced in podocytes mediated by elevated plasma glucose levels." (PMID 25139503, 2014). "Thus, the hyperglycemic environment of experimental type I diabetes contributed in part to the loss of nestin expression in the vasculature and downregulation of the intermediate filament protein may further represent an incipient event attenuating the re-entry of VSMCs in the cell cycle." (PMID 25139503, 2014). "Hyperglycaemia-mediated nestin downregulation and the concomitant reduction of cycling vascular smooth muscle cells represent early markers of vascular disease in experimental type I diabetes." (PMID 25139503, 2014). "The present study has demonstrated that the superimposition of type I diabetes on MI rats attenuated the neurogenic response of nestin(+) cells during reparative fibrosis." (PMID 23938193, 2013). "The neurogenic response of cardiac nestin(+) cells during scar formation/healing was inhibited following the superimposition of type I diabetes." (PMID 23938193, 2013). "Type 1 diabetes induced a significant upregulation in the mean fold change of relative mRNA expression of the renal cytoskeleton (stress indicators): desmin, vimentin, nestin, fibronectin-1, Coli-1, and α-SMA." (PMID 38044936, 2023). "The following study tested the hypothesis that dysregulation of nestin expression in vascular smooth muscle cells represented an early event of vascular disease in experimental type I diabetes." (PMID 25139503, 2014). "Collectively, these data support the novel premise that hyperglycaemia-mediated nestin downregulation and the concomitant reduction of cycling VSMCs represent early markers of vascular disease in experimental type I diabetes that occurred prior to the onset of impaired endothelial reactivity." (PMID 25139503, 2014). "Based on these data, the attenuated neurogenic response of cardiac nestin(+) cells during reparative fibrosis following the superimposition of type I diabetes may have been related in part to a direct effect of streptozotocin." (PMID 23938193, 2013). "In this regard, an additional series of experiments tested the hypothesis that the neurogenic response of cardiac nestin(+) cells was attenuated in a setting of type I diabetes." (PMID 23938193, 2013). "Work from our lab detected a population of cardiac resident nestin-expressing cells that exhibited a neural progenitor/stem cell phenotype and downregulation of the intermediate filament protein was identified as an incipient pathophysiological event of type I diabetes." (PMID 25139503, 2014).
viral infection (6 papers, 2011 to 2024). "But still, we were able to capture a significant reduction of stemness marker Nestin expression in proliferation hNPCs after infection, indicating the virus infection triggered abnormal neural precursor development." (PMID 25343994, 2014). "We initially used Gbaflox/flox; nestin-Cre mice in which GCase deficiency is restricted to cells of neuronal lineage, thus allowing to specifically study the effect of nGD brain pathology rather than other visceral organs on viral infection." (PMID 32831144, 2020). "In addition, viral infection was demonstrated to cause a loss of NSCs expressing CD133 and nestin." (PMID 21249143, 2011). "Additionally, viral infection caused a marked loss of NSCs expressing CD133 and nestin." (PMID 21249143, 2011). "The nestin(−) and nestin(+) populations were then examined for the presence of GFP, indicative of viral infection." (PMID 21249143, 2011). "In contrast, nestin+ cells were maintained at all dpi in CD46+ mice in comparison to mock-infected mice, suggesting that IFNγ preserves this population during a CNS viral infection." (PMID 27178303, 2016). "In addition to nestin expression, the detection of GFAP staining could be related to reactive astrocytes which are well-known as the result of cellular stress following viral infection thereby favoring tumor aggressiveness." (PMID 38553638, 2024).
adenoma (5 papers, 2014 to 2025). A neoplasm arising from the epithelium. "As previously pointed out, pleomorhic adenomas are the tumor type with the most consistent immunohistochemical expression of nestin." (PMID 33805026, 2021). "The presence of SOX2, Nestin, and CD133 was evaluated across WDLD tumors, immature PIT-1 lineage tumors, and classically differentiated adenomas using immunohistochemistry and RT-qPCR." (PMID 40643539, 2025). "Positive staining for NES, GFAP, and A2B5 in untreated cell samples made us conclude that these cells already possess the features of these cell types because of partial differentiation most probably into adenoma tissue." (PMID 27340409, 2016).
Ataxia (5 papers, 2015 to 2022). Ataxia refers to impaired coordination of voluntary muscle movement. "Both Mfp2−/− and Nestin-Mfp2−/− mice develop motor problems from the age of 4 weeks that worsen with age and eventually lead to severe ataxia and tremor." (PMID 29892213, 2018). "In contrast to the severe lethargic pathology in Mfp2−/− mice, Nestin-Mfp2−/− mice develop a milder clinical decline dominated by ataxia at a preterminal stage of disease." (PMID 29892213, 2018). "Indeed, severe cerebellar atrophy and ataxia were found in Nestin-Cre mediated deletion of Nbs1 in progenitors of CNS." (PMID 35153719, 2021). "About 12 days after tamoxifen injection, Nestin-CreERT2;QkL/L mice (hereafter denoted as ‘Qk-Nestin-iCKO mice’) began to exhibit visible tremors and ataxia accompanied by a significant reduction in coordinate movement as measured using the rotarod test and a marked growth retardation." (PMID 33942715, 2021). "Ataxia and motor impairments in both mouse models might stem from cerebellar pathology due to Purkinje cell dysfunction, which we recently demonstrated in Nestin-Mfp2−/− mice." (PMID 29892213, 2018). "Moreover, it is interesting to note that deletions of Atr in mouse neuroprogenitors (mediated by Nestin-Cre) also caused cerebellar atrophy and ataxia, although these phenotypes were absent in the Seckel Syndrome (ATR-SS)." (PMID 35153719, 2021). "Neither smooth muscle- (SM22α-Cre) nor neuron-specific (Nestin-Cre) BK channel deletions exhibit gross developmental, viability, or neurological (ataxia or tremor) phenotypes (unpublished observations)." (PMID 26537348, 2015).
cerebral infarction (5 papers, 2017 to 2019). An ischemic condition of the brain, producing a persistent focal neurological deficit in the area of distribution of the cerebral arteries. "In addition, 2 Hz EA reduced Ki67 and nestin immunoreactive cells and increased GFAP immunoreactive cells in ischemia–reperfusion-injured cerebral infarction rats." (PMID 28913350, 2017).
diabetes (5 papers, 2013 to 2023). "Our results indicated that in diabetes, Nestin+ cells mainly differentiated into vascular smooth muscle cells and promoted the occurrence of intimal hyperplasia." (PMID 35957644, 2022). "It has been shown that downregulation of nestin by podocytes in the glomerulus, is correlated with apoptosis induction in podocytes during diabetes-induced hyperglycemia." (PMID 25207540, 2014).
embryonal carcinoma (5 papers, 2014 to 2019). A non-seminomatous malignant germ cell tumor characterized by the presence of large germ cells with abundant cytoplasm resembling epithelial cells, geographic necrosis, high mitotic activity, and pseudoglandular and pseudopapillary structures formation. "Immunocytochemical analysis showed colocalization of OCTN1 with the NPC marker nestin in cultured NPCs and mouse embryonic carcinoma P19 cells differentiated into neural progenitor-like cells (P19-NPCs)." (PMID 24586778, 2014). "Further, the pluripotent embryonal carcinoma cell line NTERA-2 was used as a positive control for immunoblot analyses since these cells display characteristics of human neuronal progenitor cells and show expression of the stemness marker Nestin." (PMID 29535786, 2018). "In the current study, the epigenetic role of nuclear actin ontranscription regulation of two stemness (OCT4 and NANOG)and two differentiation) NESTIN and PAX6) marker genes was evaluated in a human embryonal carcinoma cell line (NT2)before and after differentiation induction." (PMID 27540526, 2016).
endometrial cancer (5 papers, 2016 to 2025). Primary or metastatic malignant neoplasm involving the endometrium (mucous membrane that lines the endometrial cavity). "Nestin suppression attenuates invasive potential of endometrial cancer cells by downregulating TGF-β signaling pathway." (PMID 27894083, 2016). "Endometrial CSCs isolated from endometrial cancer expressing stemness markers, including SOX2, OCT4, MYC, ABCG2, NES, and NANOG, have been demonstrated to show greater expansion potential and colony-forming capabilities, as well as to express self-renewal genes." (PMID 38539419, 2024).